EZH2 (enhancer of zeste 2 polycomb repressive complex 2 subunit)
Diseases named in the same sentence as EZH2 in open-access papers (continued):
Sharing a sentence is not in itself a finding about the gene and the disease.
esophageal cancer (continued). "Histone methyltransferase EZH2, a catalytic component of polycomb repressive complex 2 (PRC2), is highly expressed in the development of esophageal cancer." (PMID 36591447, 2022). "In esophageal cancer, lncRNA MAGI2-AS3 can recruit the histone methyltransferase EZH2 to the HOXB7 promoter region to initiate H3K27me3 and repress HOXB7 expression, resulting in enhanced tumor radiosensitivity." (PMID 35600868, 2022). "GRPEL2 and EZH2 were highly expressed in most cancer types, such as HCC, esophageal carcinoma, and stomach adenocarcinoma." (PMID 36686830, 2022). "In esophageal cancer, MAGI2-AS3 can down-regulate HOXB7 expression by recruiting the histone-lysine N-methyltransferase EZH2 (enhancer of zeste homolog 2) to promote the tri-methylation of lysine 27 on histone H3 in the HOXB7 promoter region." (PMID 34503076, 2021). "We therefore, studied the status of EZH2 and its correlation with RUNX3 expression in Indian esophageal cancer patients." (PMID 32943993, 2020). "Down-regulation of MALAT1 decreased the expression of β-catenin, Lin28 and Ezh2 genes, while over-expressed Ezh2 combined with MALAT1 down-regulation completely reversed the si-MALAT1-mediated repression of β-catenin and Lin28 in esophageal cancer cells." (PMID 27015363, 2016). "Lastly, over-expressed Ezh2 combined with MALAT1 down-regulation completely reversed the si-MALAT1-mediated repression of β-catenin and Lin28 in esophageal cancer cells." (PMID 27015363, 2016). "We show that miR-31 is repressed in invasive esophageal cancers cell lines and that miR-31 levels inversely correlate with SOX4, EZH2 and HDAC3 expression." (PMID 25644061, 2015). "To determine the expression of the complex-forming partners, SOX4, EZH2 and HDAC3, in esophageal cancer cell lines and tissues, we used qRT-PCR." (PMID 25644061, 2015). "The predictive value of EZH2 for DFS was significant for all subgroups except studies of Western patients, studies of esophageal carcinoma, and studies of quality scores ≥80.0." (PMID 25974088, 2015). "Although the mechanism of regulating cells by EZH2 and miR-200c is not yet precise, they are still promising biomarkers for treating esophageal cancer patients." (PMID 37781524, 2023). "In this study, EZH2 promoted miR-497 silencing, as well as HDAC inhibitor induced miR-497 expression levels, which firstly identified that histone modification via HDACs and EZH2 are main regulators in miR-497 downregulation in esophageal cancer." (PMID 37171386, 2023). "Thus we postulated that TRA2A regulates and activates the EZH2/β-catenin pathway by binding to MALAT1 and elevating its expression, hence promotes esophageal cancer progression." (PMID 34234858, 2021). "In esophageal cancer cells, elevated H19 expression promotes EMT and metastasis through activation of the STAT3/EZH2/β-catenin axis, and, interestingly, H19 was directly targeted by let-7c, suggesting a mutual negative-feedback regulation between H19 and let-7c." (PMID 34572067, 2021). "CCK-8 and colony formation assays showed that PSMA3-AS1 overexpression did not affect the proliferation of esophageal cancer cells with EZH2 knocked out." (PMID 32005028, 2020). "Therefore, we propose a key role for Polycomb/EZH2, HDAC and DNMT for survival and metastasis of esophageal cancers." (PMID 25644061, 2015). "However, the results showed that up-regulation of mutant PSMA3-AS1 did not increase the expression of EZH2 in esophageal cancer cells." (PMID 32005028, 2020).
liver fibrosis (36 papers, 2014 to 2025). "In three independent studies using mouse models of liver fibrosis, loss of EZH1 and EZH2 function led to the activation of fibrosis-related genes and the development or worsening of liver fibrosis." (PMID 37476157, 2023). "Loss of Ezh1 and Ezh2 in hepatocytes leads to liver fibrosis, impaired liver function and increased susceptibility to the hepatotoxic effects of carbon tetrachloride." (PMID 32428001, 2020). "We also found that Ezh1/Ezh2 deficiency up regulates many genes associated with liver fibrosis and HCC in male liver, and that these changes are seen by 7 weeks of age, which precedes the histopathological changes seen in 8-month-old mice." (PMID 32428001, 2020). "Another anti-fibrotic gene repressed by EZH2 is peroxisome proliferator-activated receptor gamma (PPARγ), a ligand-activated transcription factor that is linked to promoting protective effects against lung, cardiac, kidney, and liver fibrosis." (PMID 37476157, 2023). "For example, the lower incidence rate of liver fibrosis in women compared with men may be attributed to genes associated with liver fibrosis responding differently to the loss of Ezh1/Ezh2 in the male liver." (PMID 35281024, 2022). "The therapeutic effects of DZNep as epigenetic drug in liver fibrosis are associated with the regulation of EZH2 towards direct target genes encoding TGF-β1 pseudoreceptor BAMBI, anti-inflammatory cytokine IL10 and cell cycle regulators CDKN1A, GADD45A and GADD45B, which are also regulated by JMJD3." (PMID 33391480, 2021). "Loss of liver Ezh1 and Ezh2 can impact the onset and progression of liver fibrosis, insofar as male E1/E2-KO livers acquire a nodular appearance with portal and periportal inflammation and collagen deposition by 8 months of age, along with substantial impairment of liver function." (PMID 32428001, 2020). "RBP-J, as the primary transcription factor of the Notch signaling pathway, interacts with EZH2, inhibiting EZH2’s transcriptional activity via Hes1, thereby regulating hepatocyte senescence and liver fibrosis reversal." (PMID 39951437, 2025). "Blocking the Notch signaling pathway in macrophages can enhance hepatocyte senescence and promote the reversal of liver fibrosis by upregulating enhancer of EZH2 expression." (PMID 39951437, 2025). "The therapeutic effect of 3‐deoxyadenosine A (DZNep) as an epigenetic drug in liver fibrosis is related to Gadd45β regulation by EZH2." (PMID 39653679, 2024). "Inhibition of EZH2 helps to alleviate liver fibrosis by reducing H3K27me3 recruitment and increasing the expression of cell cycle regulators, including Gadd45β." (PMID 39653679, 2024). "The mechanisms by which EZH1/EZH2 protect against liver fibrosis were shown to involve the action of these enzymes at euchromatic chromatin bivalently marked with H3K27me3/H3K4me3 at the pro-fibrotic gene promoters." (PMID 37476157, 2023). "There are results that HBx can induce liver fibrosis also through the inhibition of the EZH2 complex." (PMID 37689710, 2023). "The repression of PPARγ by EZH2 can be alleviated in both cardiac and liver fibrosis through the overexpression of miR-214 and miR-29a, respectively." (PMID 37476157, 2023). "As the transcription of EZH2 was impeded by Notch‐Hes1 signaling, blocking Notch facilitated fibrosis regression by strengthening EZH2‐regulated senescence, providing a promising therapeutic approach for the management of liver fibrosis." (PMID 37614965, 2023). "In this study, we found that EZH2‐regulated senescent cells accumulated while liver fibrosis regression began." (PMID 37614965, 2023). "A histone deacetylase enzyme, Sirtuin 1 (SIRT1), can deacetylate EZH2 to decrease its stability and lead to the de-repression of PPARγ in liver fibrosis." (PMID 37476157, 2023). "High expression of EZH2 promotes immune activation and liver fibrosis through H3K27me3 whereas DZNep treatment attenuates hepatic inflammation and liver fibrosis in mice with autoimmune hepatitis." (PMID 36220996, 2022).
liver fibrosis (continued). "In CCl4 and BDL murine models of liver fibrosis, we assessed in vivo effects of DZNep administration and Ezh2 silencing." (PMID 33391480, 2021). "Collectively, these findings suggest that KLF14 suppression due to EZH2 elevation in fibrotic liver contributes to liver fibrosis progression by downregulating PPARγ." (PMID 34031939, 2021). "It has been proved that EZH2 plays a critical role in liver inflammation and liver fibrosis and eventually drives MAFLD progression." (PMID 34887768, 2021). "To decipher the pathological relevance of EZH2 in hepatic fibrosis, we investigated in vivo phenotypes of pharmacological inhibition and genetic knockdown of EZH2 in two murine models of liver fibrosis (CCl4 and BDL)." (PMID 33391480, 2021). "Mechanistically, some target genes of EZH2 and their functions in liver fibrosis has been characterized." (PMID 33391480, 2021). "In the present study, we found that EZH2 and JMJD3 coordinately regulate HSCs activation, pharmacological and genetic abrogation of EZH2 ameliorates liver fibrosis in murine models." (PMID 33391480, 2021). "Emerging research has demonstrated that EZH2 epigenetically regulates miRNA expression and that aberrant miRNAs are closely correlated with hepatic fibrosis." (PMID 34040893, 2021). "EZH2 was shown to promote differentiation of fibroblasts to myofibroblasts in idiopathic pulmonary fibrosis and inhibition of EZH2 reduced fibrosis-related gene expression in atrial fibrosis, liver fibrosis, and systemic sclerosis." (PMID 34070078, 2021). "EZH2 inhibitor (DZNep) was found to inhibit multiple histone methylation and was sufficient to suppress liver fibrosis by modulating histone methylation of HSC in a mouse model." (PMID 34887768, 2021). "Together, these data highlight important distinctions of TGF-β and PDGF RNA epigenetic targets including TGF-β selectivity for induction of EZH2 expression and its role in liver fibrosis." (PMID 30539787, 2019). "In vivo, we found that EZH2 inhibition attenuates liver fibrosis in the carbon tetrachloride (CCL4) and bile duct ligation (BDL) murine models." (PMID 30539787, 2019). "Recently, enhancer of zeste homolog 2 (EZH2), which methylates the lysine residues 9 and 27 of histone 3 was found to play a crucial role in experimental liver fibrosis through modulation of TGF-β signaling." (PMID 31718044, 2019). "In this study, we identify a new role of the HMT EZH2 in hepatic fibrosis through preferential induction by TGF-β as compared with PDGF-dependent pathways." (PMID 30539787, 2019). "To corroborate the in vivo effect of EZH2 inhibition in an alternative model of liver fibrosis, we performed BDL in WT mice." (PMID 30539787, 2019). "EZH2 was shown upregulated in hepatic fibrosis, along with the increase of H3K27me3 in the promoter of PPAR-γ and downregulation of PPAR-γ." (PMID 27823969, 2016). "It was shown that ASH1 and EZH2 methyltransferases are involved in development of liver fibrosis; however, their role in the resolution phase of liver fibrosis has not been investigated." (PMID 25380300, 2014). "Thirdly, ASH1 and EZH2 lysine methyltransferases were markedly induced during progression of liver fibrogenesis but were repressed during the resolution phase of liver fibrosis following mMMP-9 or HGF gene transfer." (PMID 25380300, 2014). "Future studies should evaluate the role of selective pharmacologic inhibitors of ASH1 and EZH2 in resolution of liver fibrosis." (PMID 25380300, 2014). "Prospective investigations should explore the therapeutic effect of selective pharmacologic inhibitors of ASH1 and EZH2 in the resolution of liver fibrosis." (PMID 25380300, 2014). "We have also showed that ASH1 and EZH2 methyltransferases are elevated during fibrosis progression and are repressed during the early phase of resolution of liver fibrosis." (PMID 25380300, 2014).
liver fibrosis (continued). "Only recently, very few studies investigated the role of histone lysine methyltransferases ASH1 and EZH2 during the progression of liver fibrosis." (PMID 25380300, 2014). "Additionally, EZH2 is a pivotal regulator of the TGF-β signaling pathway, and downregulation of EZH2 expression has been demonstrated to mitigate liver fibrosis induced by TGF-β." (PMID 39195573, 2024). "Treatment of activated HSCs with the EZH2 inhibitor DZNeP has been shown to alleviate liver fibrosis by downregulating miR-199a-5p expression, a process that may be modulated by EZH2." (PMID 39195573, 2024). "Indeed, DZNep, an HMT inhibitor, and GSK-503, a specific EZH2 inhibitor, prevent the progression of liver fibrosis in vivo by decreasing H3K27 methylation." (PMID 37834101, 2023). "Furthermore, DZNep-treatment or HSC-targeted Ezh2 silencing by amiRNA in diseased mice ameliorated experimental liver fibrosis." (PMID 33391480, 2021). "EZH2 inhibitor EPZ‐6438 was utilized to treat TAA‐induced rat liver fibrosis." (PMID 34031939, 2021). "KLF14 exerts a critical anti‐fibrotic role in liver fibrosis, and targeting the EZH2/KLF14/PPARγ axis might be a novel therapeutic strategy for liver fibrosis." (PMID 34031939, 2021). "Importantly, KLF14 expression was decreased in human with liver fibrosis, which was significantly correlated with EZH2 upregulation and PPARγ downregulation." (PMID 34031939, 2021). "Furthermore, KLF14 expression was negatively correlated with EZH2 expression in patients with liver fibrosis." (PMID 34031939, 2021). "Furthermore, administration of the EZH2 inhibitor GSK-503 attenuates liver fibrosis in CCl4-treated or bile duct ligation mouse models." (PMID 33207561, 2020). "In addition, activation of the NAD-dependent deacetylase SIRT1 attenuates liver fibrosis through deacetylation of EZH2, which affects the stability of EZH2 and prevents myofibroblast generation." (PMID 33207561, 2020). "Moreover, EZH2 is up-regulated in the liver of CCl4-treated rats and promotes hepatic fibrosis by repressing the Wnt pathway antagonist Dkk-1." (PMID 33207561, 2020). "Our findings suggest that targeting epigenetic modulators involved in HSC activation such as EZH2 could be useful for future liver fibrosis therapies." (PMID 30539787, 2019). "These in vivo results indicate that EZH2 inhibition attenuates murine liver fibrosis." (PMID 30539787, 2019). "Some prior studies also have addressed histone modifications and liver fibrosis including EZH2." (PMID 30539787, 2019). "In this study, we hypothesize that EZH2‐mediated suppression of Dkk1 may promote hepatic fibrosis by activating Wnt/β‐catenin pathway." (PMID 28332284, 2017). "Recently, the role of EZH2 in the development of liver fibrosis has been investigated." (PMID 25380300, 2014). "In addition, the herbal prescription Yang-Gan-Wan (YGW) and its active ingredients, rosmarinic acid (RA) and baicalin (BC), showed the potential to treat liver fibrosis by de-repressing Pparγ in an epigenetic-dependent way, which suppressed the expression of EZH2 and reduced H3K27 di-methylation." (PMID 37834101, 2023). "Therapeutic promise to target EZH2 function in a cell context-dependent manner in the liver is provided by a study using an antibody-liposome-DZNeP that was targeted specifically to HSCs and found effective in blocking the fibrotic response in an in vivo CCl4-induced liver fibrosis mouse model." (PMID 37476157, 2023). "Thus, KLF14 exerts a critical role in liver fibrogenesis, and targeting the EZH2/KLF14/PPARγ axis might provide a novel approach to liver fibrosis treatment." (PMID 34031939, 2021). "Finally, we found that liver fibrosis- and HCC-associated genes are differentially responsive to the loss of Ezh1/Ezh2 in male compared to female liver, which may contribute to the sex differences in disease incidence and progression." (PMID 32428001, 2020). "In addition, EZH2 was also reported involved in hepatic fibrosis by suppressing PPAR-γ expression." (PMID 27823969, 2016).
liver fibrosis (continued). "In liver fibrosis treatment research, when exposed to TGFβ1, SIRT1 activation substantially decreased EZH2 acetylation levels." (PMID 37985432, 2024). "Inhibition of EZH2 attenuates fibrogenic gene transcription in TGF-β-mediated HSC activation in in vitro and in vivo liver fibrosis murine models, reducing the expression of fibronectin, α-SMA, and collagen 1α1." (PMID 39408226, 2024). "EZH2 plays a critical role in the activation of HSCs through the methylation of H3K27, resulting in decreased expression of KLF14 and exacerbation of liver fibrosis." (PMID 39195573, 2024). "In contrast to EZH2’s role in promoting HSC activation for liver fibrosis, several studies suggest that EZH1 and/or EZH2 have protective roles in liver fibrosis." (PMID 37476157, 2023). "In a study using both in vitro HSCs and in vivo carbon tetrachloride (CCL4) and bile duct ligation (BDL) liver mouse fibrosis models, treatment with DZNep to block EZH2 function led to upregulated transcription of BAMBI and blocked liver fibrosis." (PMID 37476157, 2023). "Long noncoding RNAs can interact with EZH2, and maintain LSEC differentiation through KLF2-eNOS-sGC pathway and alleviate CCl4-induced liver fibrosis." (PMID 36828540, 2023). "Blocking EZH2 signaling by EPZ6438 reduced hepatic senescent cells and macrophages, decelerating liver fibrosis regression." (PMID 37614965, 2023). "Enhancer of zeste homolog 2 (EZH2), the catalytic methyltransferase subunit of the polycomb repressive complex 2 (PCR2), is another HMT that regulates HSC activation and hepatic fibrosis." (PMID 33791228, 2021). "Upon HSCs activation, the elevated EZH2 mediates suppression of KLF14 expression, which promotes HSCs activation and liver fibrosis by downregulating PPARγ." (PMID 34031939, 2021). "Collectively, the in vitro and in vivo data suggest that EZH2 inhibition by DZNep attenuates TGF-β/SMAD signaling in HSCs, inhibits HSCs activation, mitigates hepatic ECM accumulation and eventually ameliorates liver fibrosis." (PMID 33391480, 2021). "The in vitro and in vivo data collectively suggest that EZH2 and JMJD3 coordinately modulate HSCs activation and liver fibrosis through, at least in part, epigenetically regulating Bambi, Cdkn1a, Gadd45a and Gadd45b." (PMID 33391480, 2021). "Taken together, these results demonstrated that EZH2 inhibitor EPZ‐6438 upregulated KLF14 expression and ameliorated TAA‐induced rat liver fibrosis." (PMID 34031939, 2021). "We aimed to characterize the roles of H3K27 methyltransferase EZH2 and demethylase JMJD3 and identify their effective pathways and novel target genes in HSCs activation and liver fibrosis." (PMID 33391480, 2021). "In this study, we characterized divergent expressions and antagonistic functions of histone H3K27 methylase EZH2 and demethylase JMJD3 in HSCs activation and liver fibrosis." (PMID 33391480, 2021). "Therefore, EZH2 modulation could be a potential target for hepatic fibrosis treatment." (PMID 33207561, 2020). "Consequently, EZH2 modulation may be a promising epigenetic target for liver fibrosis." (PMID 30539787, 2019). "Inhibition of EZH2 attenuates fibrogenic gene transcription in TGF-β–treated HSCs and reduces liver fibrosis in vivo." (PMID 30539787, 2019). "However, the role of EZH2 in liver fibrosis is largely unknown." (PMID 28332284, 2017). "Furthermore, ASH1 and EZH2 methyltransferases were more repressed in livers of mMMP-9-treated than in livers of HGF-treated animals which may have accounted for the more effective resolution of liver fibrosis in the mMMP-9-treated animal group." (PMID 25380300, 2014). "This study evaluated the role of ASH1 and EZH2 in two mechanistically different therapeutic modalities, HGF and mMMP-9 gene transfer in CCl4 induced rat liver fibrosis." (PMID 25380300, 2014).